SERPINE2 (serpin family E member 2)
Description:
Serine protease inhibitor with activity toward thrombin, trypsin, and urokinase. Promotes neurite extension by inhibiting thrombin. Binds heparin.
Synonyms: GDN; PI-7; PN-1; PI7; PN1; PNI; nexin; GDNPF
Tractability: Antibody: its Gene Ontology location is reachable by antibodies, with high confidence; UniProt places it where antibodies can reach, with medium confidence; UniProt predicts a signal peptide or a membrane-spanning region. PROTAC: ubiquitination databases record sites on it; its protein half-life has been measured.
Gene: Protein-coding gene on chromosome 2 (223,975,045 to 224,039,688, reverse strand). Ensembl gene ENSG00000135919.
Subcellular location: Secreted, extracellular space
Subcellular location (Human Protein Atlas): Golgi apparatus; Predicted to be secreted
Pathways (Reactome):
Hemostasis: Amplification and propagation of coagulation cascade; Dissolution of Fibrin Clot; Fibrin formation; Regulation of clotting cascade
Gene Ontology:
Molecular function: glycosaminoglycan binding; heparin binding; protein binding; serine-type endopeptidase inhibitor activity; signaling receptor binding
Biological process: negative regulation of blood coagulation; negative regulation of plasminogen activation; negative regulation of proteolysis; positive regulation of astrocyte differentiation; negative regulation of platelet aggregation; negative regulation of protein processing; regulation of cell migration; negative regulation of platelet activation
Cellular component: cytosol; extracellular matrix; extracellular region; extracellular vesicle; platelet alpha granule; neuromuscular junction
Genetic constraint (gnomAD): Loss-of-function variants: 11 observed, 28.09 expected, observed/expected ratio (o/e) 0.39, 90% interval 0.25 to 0.65. The upper end of that interval is the gene's LOEUF score, 0.65, which puts it in group 2 of 6, group 1 being the genes least tolerant of losing a copy. Missense variants: 369 observed, 458.24 expected, observed/expected ratio (o/e) 0.81, 90% interval 0.74 to 0.88. Synonymous variants: 175 observed, 182.4 expected, observed/expected ratio (o/e) 0.96, 90% interval 0.85 to 1.09.
Homologues: Orthologues: chimpanzee SERPINE2 (100% identical), macaque SERPINE2 (98% identical), pig SERPINE2 (92% identical), rabbit SERPINE2 (92% identical), guinea pig SERPINE2 (92% identical), mouse Serpine2 (85% identical), rat Serpine2 (83% identical), tropical clawed frog serpine2 (72% identical), dog SERPINE2 (59% identical), zebrafish serpine2 (52% identical). Paralogues in human: SERPINE1 (40% identical), SERPINB4 (31% identical), SERPINI1 (31% identical), SERPINB3 (30% identical), SERPINB1 (29% identical), SERPINB11 (29% identical), SERPINE3 (29% identical), SERPINB6 (29% identical), SERPINC1 (29% identical), SERPINB12 (29% identical), SERPINB13 (28% identical), SERPINB10 (28% identical), and 24 more.
Diseases named in the same sentence as SERPINE2 in open-access papers:
SERPINE2 is named in the same sentence as 117 diseases in open-access papers, as found by Europe PMC text mining. Sharing a sentence is not in itself a finding about the gene and the disease. The quoted sentences say what the papers report.
breast carcinoma (36 papers, 2006 to 2025). "SERPINE2 has been found to be associated with vasculogenic mimicry in breast cancer, and the formation of vasculogenic mimicry can enhance the ability of tumor cells to metastasize to distant sites." (PMID 40356756, 2025). "Herein, we shown that SERPINE2-derived hsa_circ_0001103 (cSERPINE2) was notably elevated in breast cancer and was associated with poor clinical outcome." (PMID 36797769, 2023). "The extracellular serine protease inhibitor SERPINE2 fosters the metastasis of breast cancer cells by remodeling the extracellular matrix." (PMID 40463876, 2025). "Previous studies have reported that using SERPINE2 neutralizing antibodies can remodel the tumor microenvironment to suppress breast cancer metastasis." (PMID 40463876, 2025). "Downregulation of SERPINE2 impairs the metastatic spread of melanoma and breast cancer cells in xenografted mice, suggesting a positive role of SERPINE2 in cancer cell migration and metastasis." (PMID 38634469, 2024). "For instance, SERPINE2 overexpression promoted the metastasis of breast cancer by remodeling the tumor matrix." (PMID 36797769, 2023). "We identified oncogene SERPINE2 derived circRNA, named as cSERPINE2, which was notably elevated in breast cancer and was closely related to poor clinical outcome." (PMID 36797769, 2023). "For example, SERPINE2 overexpression promoted the metastasis of breast cancer by remodeling the tumor matrix." (PMID 38274096, 2023). "Different from cognate gene SERPINE2, overexpression of cSERPINE2 cannot encourage the malignant phenotype of breast cancer cells in vitro." (PMID 36797769, 2023). "In this work, we unraveled a novel mechanism that oncogene SERPINE2-derived hsa_circ_0001103 (cSERPINE2) functioned as communication signaling in tumor immune microenvironment to promote breast cancer progression." (PMID 36797769, 2023). "A variety of evidence showed that the extracellular serine protease inhibitor SERPINE2 fosters the metastasis of breast cancer cells by remodeling the extracellular matrix." (PMID 36797769, 2023). "We first analyzed the expression of 8 SERPINE2-derived circRNAs in breast cancer and found that only hsa_circ_0001103 (cSERPINE2) was substantially upregulated." (PMID 36797769, 2023). "In breast cancer cell lines, serpinE2 can bind to LRP1 on the cell membrane and activate the ERK1/2 signaling pathway." (PMID 36439874, 2022). "They concluded that the expression of Serpine2 and Slpi was “sufficient and necessary” to program breast cancer cells for VM, as if this combination worked as a vasculogenic inductive cocktail." (PMID 34359928, 2021). "Serpine2, which we found to be highly expressed in ES and ES-CSCs, is also highly expressed in colorectal and breast cancers, where it is reported to promote lymph node metastasis." (PMID 34403115, 2021). "SERPINE2 played an important role in metastasis in different tumors including breast cancer, melanoma, and esophageal squamous cell carcinoma." (PMID 33708105, 2020). "Of note, SerpinE2, another Serpin family member which regulates clotting, has recently been shown to be critical for VM activity of breast cancer cells." (PMID 27340778, 2016). "Using two different breast cancer models, we show that blocking serpinE2, either by knock-down (KD) in tumor cells or in response to a serpinE2 binding antibody, decreases metastatic dissemination from primary tumors to the lungs." (PMID 27793045, 2016). "The extracellular serine protease inhibitor serpinE2 is overexpressed in breast cancer and has been shown to foster metastatic spread." (PMID 27793045, 2016). "We examined a second serpinE2 KD model using human MDA-MB435 metastatic breast cancer cells and generated two KD cell lines." (PMID 27793045, 2016). "Analysis of serpinE2 in the Cancer Genome Atlas (TCGA) breast carcinoma dataset using cBioPortal, revealed that only limited numbers of tumors harbor genetic alterations (6/960), however, 61 show elevated serpinE2 mRNA levels (Fc >1.5)." (PMID 27793045, 2016).
breast carcinoma (continued). "For this we analyzed the extracellular environment of the mammary tumors in response to serpinE2 KD or to treatment with a novel serpinE2 targeted antibody." (PMID 27793045, 2016). "We have previously shown that the aggressive 4T1 mammary tumor model requires the protease inhibitor serpinE2 in order to disseminate from the primary tumor to distant organs." (PMID 27793045, 2016). "We have uncovered a role for serpinE2 in controlling the metastatic potential of mammary tumors, using KD models and a serpinE2 blocking antibody." (PMID 27793045, 2016). "SERPINE2 promotes lymph node metastasis of testicular cancer and SERPINE2 expression also correlates with selective lung metastasis in breast cancer and lymph node metastasis of oral squamous cell carcinoma." (PMID 23213280, 2012). "Recently, using mammary tumor models, it has been reported that serpinE2 stimulates metastatic spread of mammary tumors." (PMID 20942929, 2010). "In breast cancer, VM is associated with HER2-positive cases, which may contribute to two anticoagulant-secreted proteins, Serpine2 and Slpi, promoting VM formation." (PMID 40470054, 2025). "SERPINE2 is involved in the progression of some cancers, including lung cancer, renal cell carcinoma, esophageal squamous cell carcinoma, colorectal cancer, pancreatic tumors, melanoma, and breast cancer." (PMID 38274096, 2023). "Three of the top four genes enriched in PRC2+-CGI EMT pathway had not been functionally implicated in the EMT phenotype in breast cancer (SERPINE2, DKK1, MATN3)." (PMID 33931649, 2021). "These proteins were Serpine2 and Slpi, which were overexpressed in clones from a heterogeneous population of breast cancer cells that could efficiently enter the vasculature and form lung metastasis." (PMID 34359928, 2021). "However, the mechanism by which serpinE2 promotes metastasis in breast cancer models remains largely unclear." (PMID 27793045, 2016). "In addition, an analysis of 126 breast cancer patients revealed that patients with breast tumors showing elevated serpinE2 levels also had a significantly higher probability of developing lung metastasis." (PMID 20942929, 2010). "In 2015, a study on breast cancer that used molecular barcoding to follow the path of metastatic cells from the primary to the metastatic site, suggested vascular mimicry (VM) as a driver of intravasation due to the action of two secreted proteins—SERPINE2 and Slpi15." (PMID 38658568, 2024). "Given that SERPINE2 overexpression programmed breast cancer cells for vascular mimicry and contributed to distant metastasis, we wondered whether SERPINE2-derived circRNAs exerted influence on breast cancer progression." (PMID 36797769, 2023). "Moreover, the secreted protein SERPINE2 not only drives the formation of extravascular networks but also ensures cancer cell perfusion by acting as an anticoagulant, finally leading to distant metastasis of breast cancer." (PMID 36797769, 2023). "The TCGA data showed that young-age breast cancer patients have a lower level of expression of RANBP3L, GLYATL-1, and ESR1, whereas ACVR2A, SERPINE2, and PCDHGB7 have higher expression in young-age breast cancer patients compared to old age patients." (PMID 36672708, 2023). "In breast cancer, ECM proteomic analyses revealed upregulation of serpinE2 in metastatic cancer cell lines and in tumor tissues." (PMID 27793045, 2016). "Moreover, serpin family E member 2 (SERPINE2) mRNA, which induces angiogenesis in breast cancer and oral squamous cell carcinoma, is upregulated after YTHDF2 knockdown and responsible for the disruption of normal vascularization." (PMID 39691597, 2024). "Mechanistically, we suggest that the acquisition of a VM-like phenotype by breast cancer cells may be involved, as we were able to show in vitro that LDL promotes vascular invasion by tumor cells and the expression of SERPINE2." (PMID 38658568, 2024).
breast carcinoma (continued). "The Serpine2-Pleur axis was also involved in the communication of lymphatic ECs with Cxcr2+Ly6g- granulocytes, alv macrophages and classical monocytes in the lung PMN of breast cancer." (PMID 36612175, 2022). "Also, CL4 counteracted the induction of expression of the serine protease inhibitor (SERPINE2), a gene reported to be amplified in tumors with marked VM30 and recently shown to be crucial in programming aggressive breast cancer cells for VM9." (PMID 28425453, 2017). "Interestingly, an analysis of serpinE2 in the TCGA breast carcinoma dataset using the cBioPortal showed a correlation between the RNA levels of CCL2 and serpinE2." (PMID 27793045, 2016).
melanoma (20 papers, 2016 to 2025). A malignant, usually aggressive tumor composed of atypical, neoplastic melanocytes. "In human melanoma, SerpinE2 expression has previously been associated with high invasive potential of slow-cycling cells, and LHFPL2 expression was associated with mTORC1 signaling, which promotes mesenchymal-epithelial transition in cancer." (PMID 40950124, 2025). "The big data analyses have demonstrated the overexpression of SERPINE2 is strongly associated with melanoma metastasis." (PMID 33324561, 2020). "Notably, SERPINE2 has been implicated in increasing the invasivity of slow-cycling melanoma cells." (PMID 36230844, 2022). "SERPINE2 promotes melanoma metastasis through the glycogen synthesis kinase 3β (GSK-3β) signaling pathway." (PMID 36505099, 2022). "SERPINE2 promoted melanoma metastasis through the glycogen synthesis kinase 3β (GSK-3β) signaling pathway in a mouse model." (PMID 35646893, 2022). "Compared with those in the low-risk group, the melanoma patients in the high-risk group had high expression of S100A11 and CPC3 and low expression of PSME2, ARID5A, and SERPINE2 and had a shorter survival time." (PMID 35646893, 2022). "report that down-regulated expression of Serpine2 can strikingly inhibit the metastasis of melanoma cells in vivo." (PMID 33324561, 2020). "In the present study, we developed a prognostic and diagnostic biomarker with 5 selected MRGs (A2M, DUSP6, HLA-B, SERPINE2, and SLC26A2), all of which acted as risk factors in melanoma." (PMID 33324561, 2020). "However, studies have shown that SERPINE2 promotes the metastasis of melanoma cells through the GSK-3β signaling pathway both in vitro and in vivo." (PMID 40356756, 2025). "Whether SERPINE2 promotes vasculogenic mimicry in melanoma brain metastasis needs further validation." (PMID 40356756, 2025). "SERPINE2 could also promote melanoma metastasis through the glycogen synthesis kinase 3β (GSK-3β) signaling pathway." (PMID 35646893, 2022). "SERPINE2 was critical for melanoma invasion and correlated with tumor progression." (PMID 35646893, 2022). "Interestingly, several protease inhibitors, such as TIMP1, TIMP3, and SERPINE2, were also upregulated in metastatic primary melanomas." (PMID 26918341, 2016). "Similarly, the activity of SERPINE2 stimulates the melanoma metastatic behaviour." (PMID 33182777, 2020). "In addition, SerpinE2 appears to be involved in the maintenance and invasiveness of CSCs in melanoma, and the inhibition of this proteolytic enzyme has been speculated to be a potential therapeutic target." (PMID 33202944, 2020). "First, we identified tumor cells by inferred large-scale CNVs from single-cell expression profiles and newly identified PMEL, S100B, SERPINE2, TYR, and PRAME as marker genes for melanoma malignant cells." (PMID 35646893, 2022). "It has been shown that YTHDF2 targets a plethora of mRNAs for degradation in cancers, such as, TNFR2, c-Myc and CEBPA in leukemia, EGFR, IL11, SERPINE2 and SOCS2 in liver cancer, and PD-1, CXCR4, and SOX10 in melanoma." (PMID 33658012, 2021). "In addition, PSME2 and other four gene markers for malignant cells (ARID5A, SERPINE2, GPC3, and S100A11) were combined to develop a prognostic signature in melanoma." (PMID 36583022, 2022). "PMEL, S100B, SERPINE2, TYR, and PRAME were highly expressed in tumor cells and could be the marker genes for melanoma." (PMID 35646893, 2022).
colorectal cancer (10 papers, 2010 to 2025). A primary or metastatic malignant neoplasm that affects the colon or rectum. "KEGG analysis revealed a significant enrichment of the gene set in metabolic pathways, suggesting a potential association between SERPINE2 and metabolic reprogramming in colorectal cancer." (PMID 40463876, 2025). "Subsequently, we conducted an analysis of various online databases and found that SERPINE2 is closely associated with malignant progression in colorectal cancer." (PMID 40463876, 2025). "SERPINE2, a member of the serine protease inhibitor nexin superfamily, contributes to the invasion in solid tumours and more specifically in colorectal cancers bearing KRAS or BRAF mutations." (PMID 30651148, 2019). "To dissect the gene network of SERPINE2 in colorectal cancer, we obtained a set of genes related to SERPINE2 expression in colorectal cancer through cbioportal." (PMID 40463876, 2025). "As an important secretory factor in the tumor microenvironment, we investigate the relationship between SERPINE2 and immune cells in colorectal cancer." (PMID 40463876, 2025). "In this study, we observed a high expression of SERPINE2 in colorectal cancer and identified it as an outstanding prognostic marker associated with the clinical progression of the disease." (PMID 40463876, 2025). "This offers new perspectives into targeting SERPINE2 as a potential therapeutic target for colorectal cancer." (PMID 40463876, 2025). "In conclusion, our study evaluated the expression levels and prognostic value of SERPINE2 in colorectal cancer, revealing its relationship with the immune tumor microenvironment and interaction with tumor-associated macrophage." (PMID 40463876, 2025). "In order to analyze the potential functions and pathways of the SERPINE2 in colorectal cancer, cbioportal database was utilized to conduct co-expression analysis of the SERPINE2 gene." (PMID 40463876, 2025). "The upregulation of SERPINE2 in colorectal cancer has been found to increase the infiltration of tumor-associated macrophages." (PMID 40463876, 2025). "SERPINE2 is overexpressed in a variety of adenocarcinomas, including breast cancer, pancreatic cancer, gastric cancer, and colorectal cancer, and its high expression is correlated with the degree of cancer malignancy." (PMID 33317533, 2020). "SERPINE2 expression is elevated in colorectal cancer, correlates with tumor grade and its silencing reduces anchorage-independent growth, migration, and tumor formation." (PMID 23213280, 2012). "Accordingly, we found an upregulation of serpinE2 mRNA levels in human adenomas and colorectal cancer tissues as compared to corresponding normal tissues." (PMID 20942929, 2010). "In the present study, we show that RNA interference (RNAi) targeting serpinE2 in MEK1-transformed rat IECs or in human colorectal cancer cells decreased anchorage independent growth, migration and tumor formation in nude mice." (PMID 20942929, 2010). "While further studies are needed to pinpoint the molecular mechanisms by which serpinE2 regulates tumor cell growth and migration, the present study provides novel fundamental insights into the function of serpinE2 in colorectal cancer progression." (PMID 20942929, 2010). "Of note, expression of serpinE2 in human colorectal cancer cell lines was shown to be dependent, at least in part, of endogenous activities of MEK/ERK." (PMID 20942929, 2010). "Using a trypsin-mediated de-adhesion assay, downregulation of serpinE2 significantly delayed LoVo cell detachment after trypsinization, suggesting that serpinE2 expression decreases adhesion of colorectal carcinoma cells to the substrate." (PMID 20942929, 2010). "Additionally, we have uncovered a novel mechanism that SERPINE2 functions as a signaling molecule in the tumor immune microenvironment, promoting the advancement of colorectal cancer." (PMID 40463876, 2025).